IL17A (interleukin 17A)
Diseases named in the same sentence as IL17A in open-access papers (continued):
Sharing a sentence is not in itself a finding about the gene and the disease.
gastric cancer (continued). "Neutrophils in the stroma of gastric cancer (GC) produce IL17a and CXCL5 both promoting EMT, indicated by upregulation of VIM and ZEB1, whereas CDH1 is repressed." (PMID 34459003, 2021). "Additionally, IL-17A has been reported to have a role in promoting tumor growth and metastasis, but it also exhibited anti-cancer ability and showed a positive function in improving response to adjuvant chemotherapy in bladder cancer and gastric cancer." (PMID 34079795, 2021). "The aim of this study is to investigate the effect of IL-17A on the invasiveness of gastric cancer (GC)." (PMID 24905806, 2014). "Inhibition of this pathway, using IL-17A neutralizing antibodies or the JAK2-specific inhibitor AG490, reverses these TAN-induced phenotypes in gastric cancer cells." (PMID 40387965, 2025). "TANs secrete IL-17A via the JAK2/STAT3 signaling pathway, which promotes EMT in gastric cancer cells." (PMID 40387965, 2025). "In patients with gastric cancer at stages I, II, and III of the disease, there is an increase in such proinflammatory cytokines as TNF-α, IL-2, IL-8, TNF-β, IL-17A, and IL-6, as well as a decrease in IFNγ." (PMID 40806737, 2025). "In gastric cancer tissues, neutrophils produce IL-17A, and TANs-derived IL-17A promotes the migration, invasiveness, and EMT of gastric cancer cells by activating the JAK2/STAT3 pathway." (PMID 40387965, 2025). "TANs secrete IL-17a, enhancing the migration, invasion, and EMT of gastric cancer cells, while activating the JAK2/STAT3 signaling pathway in these cells." (PMID 39676857, 2024). "IL-17A produced by neutrophils exacerbates tumor growth by inducing CXC chemokines (CXCL1, CXCL2, CXCL3, CXCL5, CXCL8, and CXCL11) in gastric cancer cells to recruit neutrophils to the invasive edge." (PMID 39906741, 2024). "In gastric cancer stroma, neutrophils promote tumor metastasis by inducing EMT through secreting CXCL5 and IL-17a, whereas antibody-mediated IL-17a blockade suppresses EMT in cancer cells cocultured with TANs." (PMID 36091114, 2022). "Hence, we thought that the addition of agents (for example: IL-17A mAb, IL-6 mAb) against inflammation to the basic treatment including chemotherapy, palliative surgery etc would probably be a promising strategy for patients with initial stage IV gastric cancer." (PMID 35436305, 2022). "Antibodies that neutralize IL-17a reduce tumor progression in gastric cancer (GC) cells." (PMID 36060811, 2022). "In patients with gastric cancer at stage IV of the disease, multidirectional changes occur when studying proinflammatory cytokines: a decrease in TNF-α, IL-8, TNF-β, as well as an increase in IL-2, IFNγ, IL-17A, and IL-6." (PMID 40806737, 2025). "Secondly, IL-17A also activates the NF-κB/NADPH oxidase 1 (NOX1) signaling pathway by binding to IL-17RA and IL-17RC, and promotes the cell cycle transition from G1 to S phase, thereby promoting the proliferation of gastric cancer cells." (PMID 39906741, 2024). "Among them, INF-γ, IL-17 and IL-21, and B-cell inflammatory genes are significantly increased in people with CAD, and IL-17a promotes the epithelial to mesenchymal transition in gastric cancer cells through JAK2/STAT3, exacerbating the development of gastric cancer." (PMID 36970364, 2023). "Concerning the linkage between cytokines and the HADS-D score, only IFN-γ (P = 0.049), but not IL-4 (P = 0.065) or IL-17A (P = 0.058), was positively linked to the HADS-D score in elderly gastric cancer patients." (PMID 36386524, 2022). "Our study elucidates the immunosuppressive role of Tc17 cells in the gastric cancer microenvironment, particularly their recruitment by tumor cells via the CXCL16-CXCR6 axis and subsequent promotion of tumor progression through the secretion of cytokines such as IL-17A and IL-26." (PMID 40452847, 2025).
gastric cancer (continued). "Although numerous studies have shown that IL‐17A and its downstream signaling contribute to poor prognosis in several cancers, including osteosarcoma, NSCLC gastric cancer, pancreatic carcinoma and CRC,4, 10, 15, 16, 20 the role of IL‐17RA in tumor development and progression remains unclear." (PMID 38491831, 2024). "In addition, 15×19 CAR T cells did not produce IL-4, IL-10, or IL-17A cytokines upon stimulation by gastric cancer cells." (PMID 36618357, 2022). "We found that RORγ and IL-17A, the main Th17 factors, are highly upregulated in gastric mucosa derived from both H. pylori infection and gastric cancer suggesting a link between H. pylori infection, the inflammatory CD4+ T cell phenotype, Th17, and gastric cancer." (PMID 23365642, 2013). "TANs produce IL-17a, which promotes EMT of GC cells through JAK2/STAT3 signaling in gastric cancer." (PMID 40564191, 2025). "Based on transcriptome data analysis revealing elevated expression of IL17A and IL26 in gastric cancer tissues, we systematically evaluated the impact of these two cytokines on malignant biological behaviors of GC tumor cells through in vitro functional experiments." (PMID 40452847, 2025). "Similar to our results, a gastric cancer study found that neither G-CSF, GM-CSF, TGF-β, M-CSF, IL-1β, IL17A, IL-6, TNFα, IL10, IFNγ and IL22 were able to induce MC degranulation, while only adrenomedullin did." (PMID 32722549, 2020).
melanoma (136 papers, 2010 to 2026). A malignant, usually aggressive tumor composed of atypical, neoplastic melanocytes. "Although the pathophysiological mechanisms by which IXE contributes to melanoma development remain unclear, studies in melanoma animal models have demonstrated that IL-17A-deficient mice are susceptible to developing spontaneous melanoma." (PMID 41158454, 2025). "Furthermore, basal levels of IL-17a in melanoma patients were associated with poor clinical outcomes." (PMID 38236249, 2024). "Furthermore, other investigators using animal models of melanoma have shown that IL-17A-deficient mice are susceptible to spontaneous melanoma development." (PMID 38927967, 2024). "However, a recent study has shown that high levels of IL-17A in the baseline peripheral blood of patients with melanoma are associated with better clinical responses to dual ICB therapy (anti-PD-1 + anti-CTLA-4)." (PMID 38675738, 2024). "Deficient IFN-γ or IL-17A impaired Th17 cell-mediated melanoma eradication effect." (PMID 30800130, 2019). "This concurs with findings that the TRAF2/PIAS2/ELAVL1/EPHA5 pathway is pivotal in IL-17A-induced melanoma." (PMID 40809015, 2025). "Treatment with rm-IL-17A led to increased mRNA expression of key T cell chemokines such as CXCL9–CXCL11, adhesion molecules ICAM1 and VCAM1 and IL-17-dependent cytokines in melanoma cells." (PMID 37525015, 2023). "We confirmed that several IL-17 signaling genes were expressed at a significantly higher level in BM neutrophils stimulated with conditioned medium from intrinsically ICI-sensitive mouse melanoma and that this was abrogated by concurrent α-IL-17A treatment." (PMID 37525015, 2023). "We first generated conditioned medium from untreated and rm-IL-17A-treated ICI-sensitive CM mouse melanoma cells (tumor conditioned medium)." (PMID 37525015, 2023). "PDTFs from three ICI-responsive patient melanomas were treated with dual ICI in the absence or presence of α-IL-17A." (PMID 37525015, 2023). "Roesch and colleagues use clinical datasets and mouse models of BRAF-mutant melanoma to reveal a role for IL-17A in positive responses to anti-PD-1 and anti-CTLA-4 therapy, which they also link to infiltrating neutrophils." (PMID 37525015, 2023). "IL-17A induces the expression of inflammatory cytokines IL-1β, IL-16 and IL-23 in the tumor microenvironment in malignant melanoma." (PMID 36135194, 2022). "Previously published data indicated that murine and human melanoma cell lines expressed the IL-17 receptor (R) and responded to IL-17A stimulation." (PMID 34944746, 2021). "As we have previously shown that different skin tumor types proliferated in response to IL-17A treatment both in vitro and in vivo, we evaluated by flow cytometry expression of IL-17 receptor (R)A in six human melanoma cell lines." (PMID 34944746, 2021). "Markedly higher levels of IL‐17A in the serum and lung were observed in aged mice after the B16/F10 melanoma challenge." (PMID 31903715, 2020). "Antibiotics treatment resulted in a decreased frequency of γδT cells and impaired IL-17A + γδT cells in the lungs after challenged with B16/F10 melanoma cells." (PMID 28785009, 2017). "We tested a battery of cytokines, including IL-8, TNFα, MIP1, MCP1, IL-4, and IL-17a, in pretreatment (basal) serum samples of melanoma patients who responded to TIL treatment (n = 8) as compared with patients who failed to respond (n = 8)." (PMID 26688824, 2015). "Recent studies have shown an involvement of immune system dysregulation in pathophysiology of mucosal melanomas with identification of certain genes like IL17A and CD70." (PMID 24995141, 2014). "A recent evaluation of melanoma patients receiving combination anti-CTLA-4 and anti-PD-1 found that increased IL-17a/IL-17f signaling was positively associated with immune infiltration and improved clinical outcomes; however, this relationship did not extend to patients treated with monotherapy." (PMID 39403935, 2024).
melanoma (continued). "Studies reveal context‐dependent effects of IL‐17A in cancer, demonstrating instances of Th17‐mediated anti‐tumor immunity and IL‐17A‐producing cells contributing to CD8+ T cell exhaustion in melanoma, ultimately enhancing the efficacy of immunotherapeutic approaches." (PMID 38585232, 2024). "Interestingly, a significative lower frequency of IL-17A positive cells was detected in primary melanomas of patients developing vitiligo during therapy in respect to patients not developing this irAE." (PMID 37680638, 2023). "Consistently with the observed blood reduction of Th17 cells in melanoma patients developing vitiligo during immunotherapy, we found high amount of IL-17A expressing cells in the vitiligo skin biopsy, suggesting a possible migration of Th17 cells from the blood into the autoimmune lesion." (PMID 37680638, 2023). "Consequently, conditioned medium from rm-IL-17A-treated melanoma cells attracted more CD8+ T cells than conditioned medium from untreated cells (P = 0.0434)." (PMID 37525015, 2023). "Finally, high IL-17A levels in the blood of patients with melanoma indicated a higher global TH17 cytokine profile preceding clinical response to dual ICI but not to anti-PD-1 monotherapy, suggesting a future role as a biomarker for patient stratification." (PMID 37525015, 2023). "Therefore, we focused on IL-17A for our cytokine-based approach for outcome stratification of patients with melanoma." (PMID 37525015, 2023). "Indeed, IL-17A promotes angiogenesis and induces IL-6 production in murine melanoma models, which in turn activates STAT3, upregulating the expression of angiogenesis and survival-supporting genes." (PMID 33466236, 2021). "An additional hypothesis for such specific immunosuppression performed by melanoma cells in respect to Th-17 lymphocytes could be that melanoma cells were inhibited by IL-17A, and therefore, have found a mechanism to block IL-17A-producing cells." (PMID 34944746, 2021). "The markedly shortened survival time in the anti‐γδTCR mAb‐treated aged mice compared with the anti‐TCRVγ4‐treated aged mice demonstrated that the Vγ6+γδT cells with high ability to produce IL‐17A also exhibited important anti‐tumor activity in the development of B16/F10 melanoma in aged lungs." (PMID 31903715, 2020). "Neutralization of IL‐17A using an anti‐IL‐17A mAb in aged mice significantly reduced the mean survival time from 45.10 to 38.20 days, demonstrating the critical anti‐tumor role of IL‐17A in the development of B16/F10 melanoma in aged lungs." (PMID 31903715, 2020). "When the normal alveolar macrophages were transferred or the higher levels of CCL24 were neutralized, the frequency and number of γδT cells, particularly IL-17A + γδT cells, significantly increased in the lungs of the Abt mice after challenged with B16/F10 melanoma cells." (PMID 28785009, 2017). "IL-17A stimulation recruits ELAVL1 and PIAS2 via TRAF2, stabilizing EPHA5 mRNA and promoting melanoma cell proliferation and invasion." (PMID 40809015, 2025). "The levels of IL-6, IL-8, IL-10, IL-17A, IL-27, IL-31, GM-CSF, IFN-α, IL-9, VEGF-D, TNF-β, NGFβ, IL-23, IL-22, and IL-1α were below the threshold of detection in both melanoma patients and healthy controls." (PMID 33574842, 2021). "And these cells produced elevated levels of IL-17A and IFN-γ and developed a distinct memory phenotype with elevated expression of CD44 and CD62L during response to established melanoma while untreated cells mainly presented effector phenotypes in melanoma." (PMID 30800130, 2019). "Notably, four clinical trials on myeloma, diffuse large B cell lymphoma (DLBCL), melanoma, and NSCLC are ongoing which combine anti-PD1 antibody and IL-17A (NCT03111992), CD22 (NCT03287817), KIT (NCT04493203), or AXL (NCT04681131), respectively." (PMID 38349411, 2024).
melanoma (continued). "Next, we isolated naive bone marrow (BM) neutrophils from C57BL/6N mice and cultured them in conditioned medium derived from ICI-sensitive CM melanoma cells with or without α-IL-17A for 24 h." (PMID 37525015, 2023). "To understand whether IL-17A is also a relevant contributor to CTLA-4 and PD-1 blockade in human melanomas, we used an ex vivo patient-derived tumor fragment (PDTF) model, which has recently demonstrated high predictive capacity for ICI22,23." (PMID 37525015, 2023). "The expression of LL-37 on myeloid cells in dermis is correlated with levels of proinflammatory cytokines such as IL-23p19, IL-17A, and TNF-α, which could promote tumor progression via angiogenesis in melanoma and non-melanoma skin cancers." (PMID 36980564, 2023). "Moreover, when NOD mice were inoculated with melanoma or colon carcinoma tumor cells, increased ICI-induced thyroid Th17 and Tc17 was observed that was reduced with IL-17A neutralizing Ab." (PMID 37445704, 2023). "To study the effect of the systemic IL-17A level on the anti-tumor efficacy of ICI therapy in vivo, we used two syngeneic melanoma transplantation models with distinct genotypes and response profiles to experimentally administered anti-CTLA-4 and anti-PD-1 antibodies." (PMID 37525015, 2023). "Treg signature genes CXCR5, TNFRSF9, CCR7, STAT1, GBP4, and EOMES were significantly upregulated in the young cohort and were correlated with higher survival in melanoma, while ID3, IL-17A, IL-17F, RDH10 and IL-11 were significantly upregulated in the old cohort." (PMID 36135194, 2022). "JQ1 was characterized by induction of inhibitory relationship linking regulators of inflammation (IFNG, IL17A, TGFB2), melanoma biological behavior (EGFR, WNT3A, TEADs, MRTFB), cell-cell interaction (CD44, CCN2), YAP pathway (LLGL2, NSUN6) and main transcriptional regulators (FOS, JUN, FOXM1)." (PMID 36397155, 2022). "In the histological specimens examined, we did not detect a direct IL-17A expression by melanoma cells as was previously reported." (PMID 34944746, 2021). "Also, low levels of IL‐17A and high levels of IFN‐γ production in lung CD4+T and NKT cells were detected in the aged mice after the B16/F10 melanoma challenge." (PMID 31903715, 2020). "In a mouse model, adoptively transferred Th17 polarizedcells were able to mediate destruction of advanced B16 melanoma and induce vitiligo,but this therapeutic effect was critically dependent on IFN-γ production,whereas IL-17A and IL-23 depletion had little impact." (PMID 21541348, 2011). "Also, and consistently with the observed blood reduction in Th17 cells in melanoma patients developing ICI-induced VLLs, there was a high number of IL-17A-expressing cells in the vitiligo skin biopsy, suggesting a possible migration of Th17 cells from the blood into the autoimmune lesion." (PMID 38392077, 2024). "Interestingly, our analysis of primary melanomas from patients who developed or not vitiligo under anti-PD-1 therapy showed a higher number of IL-17A-expressing cells in the tumor samples of patients not developing vitiligo." (PMID 37680638, 2023). "However, in our hands, melanoma cells did not express IL-17RA in vitro and would not respond to IL-17A stimulation." (PMID 34944746, 2021). "Further, by selectively targeting this particular isoform, melanoma patient derived PBMC response activity in vitro was increased significantly with higher production of the T cell effector cytokines IFN-γ and IL-17A when compared with non-selective ipilimumab." (PMID 35069536, 2021). "We also evaluated the protein amount of a set of 12 cytokines and chemokines, including IL-2, IL-4, IL-5, IL-6, IL-10, IL-12, IL-17A, TNF-α, IFN-γ, MCP-1, MIP-1α, and eotaxin in TIF and plasma samples of C57BL6 mice, engrafted or not engrafted with B16 melanoma cells." (PMID 34604232, 2021).
melanoma (continued). "In a first analysis including the entire cohort of recruited patients (in situ and stage I–IV melanoma patients), the amount of GM‐CSF, IL4, IL‐6, IL‐10, IL‐17A, and TGF‐β detected in serum was independent of the age of the melanoma patients and it did not vary between the sexes." (PMID 32485045, 2020).